FOXP1 (forkhead box P1)
Diseases named in the same sentence as FOXP1 in open-access papers (continued):
Sharing a sentence is not in itself a finding about the gene and the disease.
cancer (continued). "For instance, nine of our candidate cancer genes were also contained in the Cancer Gene Census list, which comprises 487 genes causally linked to cancer, representing a highly significant enrichment (Abl2, Braf, Fbxw7, Foxp1, Ipo11, Mllt3, Fas, Pten, and Nf1; p<0.0002, Fisher’s exact test)." (PMID 23940809, 2013). "In addition, SNP rs62247035 at 3p13 is intronic in forkhead box P1 (FOXP1), a gene that encodes a transcriptional factor that regulates lymphocyte development and whose abnormal expression has been demonstrated in various human cancers." (PMID 35449187, 2022). "Therefore, FOXP1 is associated with cancer patient prognosis in a context-dependent manner." (PMID 29848352, 2018). "Therefore, we speculated that EBV may alter immune cell differentiation and the inflammatory process, in order to promote inflammation-induced carcinogenesis in EBV-associated cancers by inhibiting FOXP1 expression." (PMID 27167345, 2016). "FOXP1 plays a critical role in sustaining stemness in embryonic stem cells and exhibits similar functions in cancer stem cells." (PMID 40169859, 2025). "We analyzed the expression of FOXP1 in three cohorts of cancer patients who received ICB treatment to determine if FOXP1 expression correlated with their response to therapy." (PMID 40672953, 2025). "Specifically, we show that cancer-induced FoxP1 rewires the skeletal-muscle circadian transcriptome toward pathways associated with muscle wasting and disrupts the temporal patterning of pathways governing glucose, lipid, and oxidative metabolism." (PMID 40349340, 2025). "Prospective clinical studies and animal models are crucial to further confirm the diagnostic and therapeutic value of FOXP1 in AML and other cancers." (PMID 40672953, 2025). "We further found that skeletal-muscle FoxP1 modulates core clock gene expression in response to cancer, including repression of core clock activators and activation of core clock repressors." (PMID 40349340, 2025). "Previous literature suggests that FOXP1 can promote cancer progression and participates in the senescence processes of various organ tissues." (PMID 40702440, 2025). "Our study provides compelling evidence for targeting FOXP1 to identify and combat CSCs in chemoresistant cancers." (PMID 40169859, 2025). "Given the complex and context-dependent roles of FOXP1 in different cancers, a systematic analysis of its expression, prognostic significance, and immune-related functions in hematologic malignancies is crucial." (PMID 40672953, 2025). "Overall, these findings demonstrate that genes annotating to pathways of protein turnover gain rhythmicity in skeletal muscle in response to cancer, showing time-of-day-dependent increases in gene expression, which occurred in a FoxP1-dependent manner." (PMID 40349340, 2025). "While these findings provide valuable insights into its function in specific malignancies, our study extends beyond individual cancers by systematically analyzing FOXP1 across various hematologic malignancies." (PMID 40672953, 2025). "As research has progressed, the involvement of FOXP1, and by extension circFOXP1, in cancers and other diseases has become evident." (PMID 39606233, 2024). "In BC cells, PRMT5 is recruited to the Forkhead Box P1 (FOXP1) promoter, a winged helix/forkhead transcription factor associated with cancer stem cell function and facilitates H3R2 methylation." (PMID 39201539, 2024). "Despite the many studies on the role of FOXP1 in other cancers, its role in ICC was first revealed by the present study." (PMID 38279090, 2024). "FOXP1, a member of the forkhead box protein family, is widely expressed in human tissues and plays a role in embryonic development, immune regulation, and cancer progression." (PMID 38279090, 2024).
cancer (continued). "One deletion SV in all members of LRLS impacts FOXP1, a gene correlated to several cancers including esophagogastric, gastrointestinal, and CRC in the My Cancer Genome database." (PMID 37627102, 2023). "The winged helix transcriptionfactor forkhead box P1 (FOXP1) is reported as either an oncogene ortumor suppressor in various cancers." (PMID 37546627, 2023). "FOXP1 interferes with cell cycle G1/S phase arrest by downregulating dephosphorylated Rb, thereby dysregulating the cell cycle and contributing to cancer development." (PMID 37035153, 2023). "The Foxp family, which is composed of Foxp1, Foxp2, Fxop3 and Foxp4, is also involved in diverse biological processes including development, immune disorders and cancer progression." (PMID 35974052, 2022). "Other members of the FOX family of TFs such as FOXA1, FOXM1, and FOXP1 are considered oncogenes and FOXC1 was implicated in cancer stemness through modulation of β-catenin signaling." (PMID 35349489, 2022). "Several TFs have been reported to regulate immune cell infiltration in cancer, such as FOXP1, FOXP3, and c-Maf." (PMID 34489925, 2021). "Microarray analysis on tibialis anterior pooled samples revealed FoxP1 as a key mediator of the cancer‐induced transcriptional repression of gene networks critical to muscle structure, function, and regeneration/repair." (PMID 33527776, 2021). "In support of these findings, FOXP1 mRNA levels were significantly higher in PDAC patients classified as cachectic compared with weight‐stable non‐cancer controls, which aligns with our finding of increased abundance of FOXP1 protein." (PMID 33527776, 2021). "Upregulated expressions of E2A, FOXO1, or FOXP1 enhanced RAG1 expression, while silencing of E2A, FOXO1, or FOXP1 decreased RAG1 expression in the cancer cells." (PMID 34226529, 2021). "Our present data extend this previous work by showing that skeletal muscle expression of FoxP1 is increased in multiple models of cancer cachexia in which FoxO factors are also elevated, and by further identifying FoxP1 as a downstream target of FoxO1." (PMID 33527776, 2021). "Herein, we investigated the biological significance of Forkhead box P1 (FoxP1), a transcriptional repressor that we demonstrate is up‐regulated in skeletal muscle in multiple models of cancer cachexia and in cachectic cancer patients." (PMID 33527776, 2021). "Using skeletal muscle biopsies from cancer patients, we demonstrate that these findings are relevant to human cancer cachexia, because the levels of FOXP1 mRNA and protein were elevated in patients defined as cachectic." (PMID 33527776, 2021). "Five cryptically spliced genes (ANKHD1, ATM, FOXP1, MAP3K7, and TTI1), identified in previous transcriptomic analyses in SF3B1-mutated patients, were analyzed in different cancer types." (PMID 33585229, 2020). "Common CNLs negatively influencing DFS and cancer-specific OS harboured the feline orthologous of multiple HBC-related genes reported as commonly deleted including FOXP1, FBXO25, CSMD1, AGPAT5, PCM1, PTPRG, and PDGFRL15,19,27,28,41–43." (PMID 31969654, 2020). "FOXP1 has been reported to be a transcription factor that participates in the regulation of multiple cancers." (PMID 33006432, 2020). "It has been reported that FOXP1 overexpression potentiated Wnt/β-catenin signaling in diverse cancer cell types." (PMID 32874129, 2020). "In NPC and GC, ebv-mir-BART11-3p and 5-p induce cancer cell proliferation through the suppression of forkhead box P1 (FOXP1)." (PMID 32033193, 2020). "Remarkably, FOXP1 is identified to act as an oncogene, and its overexpression confers a poor prognosis in various types of cancers." (PMID 32584787, 2020). "As we currently understand normal anti-cancer responses, a functional immune system is a key component that suppresses cancer: Foxp1 controls mature B-cell survival and development, and is a regulator for CD4+ T cells." (PMID 32577159, 2020).
cancer (continued). "FOXP1 is involved in the transcriptional regulation and plays vital roles in immune responses, cell differentiation, and cancer progression." (PMID 31170987, 2019). "Browsing further blood malignancy conditions identifies FOXP2 as a putative marker for DLBCL, in line with previous observations that FOXP1 is a determinant oncogenic driver in these cancer types." (PMID 29725501, 2018). "Main mechanisms leading to FOXP1 protein overexpression in cancers are translocations, amplifications, or the repression of miRNAs normally downregulating FOXP1 translation." (PMID 29352181, 2018). "In cancer cells, FOXP1 has been suggested as both a potential oncogene and tumor suppressor depending on the cellular context." (PMID 26654944, 2016). "Many studies have revealed that FOXP1 is aberrantly expressed in several types of cancers and its expression frequently has a significant correlation with aggressive malignant phenotypes of tumors and poor prognosis in patients." (PMID 27618020, 2016). "The nearest gene to this association signal is forkhead box protein P1 (FOXP1), which encodes a transcription factor regulating esophagus development and acts as therapeutic target in cancer 4,5." (PMID 26383589, 2015). "FoxP1 (Proteins of the Forkhead-box family) has also been revealed to be expressed in many types of human malignant tumors, while it is along with metastasis." (PMID 23874428, 2013). "In vivo chromatin immunoprecipitation (ChIP) assay showed that the histone H3 of Erag was acetylated and that E2A, FOXO1, FOXP1 were bound to Erag in these cancer cells." (PMID 21655267, 2011). "In this study, we focused on a selected number of transcription factors and found that E2A, FOXO1 and FOXP1 regulated RAG expression in cancer cells." (PMID 21655267, 2011). "At the protein level, E2A, FOXO1, FOXP1 and NF-κB subunit p65 were all detected in the cancer cells with Western blot assay." (PMID 21655267, 2011). "In this study, we first analyzed the protein and mRNA expressions of those transcription factors that have been found to be essential for RAG activation in B cells, including E2A (E47 and E12), FOXO1, FOXP1, Ikaros, NF-κB, and PAX5β, in four cancer cell lines." (PMID 21655267, 2011). "By RT-PCR, Western blot and immunofluorescence, we found that transcription factors E2A, FOXO1 and FOXP1 were expressed and localized to the nuclei of these cancer cells." (PMID 21655267, 2011). "Here we have shown that FOXO1 and FOXP1 also have regulatory function in RAG expression in cancer cells." (PMID 21655267, 2011). "RT-PCR results showed that FOXO1, FOXP1, NF-κB subunit p65 and both of the two isoforms of E2A (E47 and E12), were expressed in the cancer cells A549, PC3, MCF-7 and MDA-MB-231." (PMID 21655267, 2011). "Similar to their role in the activation of RAG expression in B cells, we found that E2A, FOXO1 and FOXP1 regulated RAG expression in cancer cells by binding to Erag." (PMID 21655267, 2011). "We found that E2A, FOXO1 and FOXP1 were expressed in cancer cells and localized to the nuclei of these cells." (PMID 21655267, 2011). "Based on the molecular weight, the full length FOXP1 was found to be the main isoform of FOXP1 expressed in the cancer cells." (PMID 21655267, 2011). "The results showed that E2A and FOXP1 were predominantly localized to the nucleus, whereas NF-κB was exclusively localized to the cytoplasm of the cancer cells." (PMID 21655267, 2011). "FOXP1 is a potential therapeutic target in cancer and can be considered either an oncogene and/or a tumor suppressor gene." (PMID 20969748, 2010). "Consequently, we propose that FOXP1 is a potential immunotherapeutic response biomarker for some cancer types." (PMID 40672953, 2025).
cancer (continued). "Several of the direct FOXP1 targets upregulated in response to cancer were transcriptional repressors of the circadian clock, including Kfl9, Nr1d1, Per1, and Bhlhe40, providing further evidence that FOXP1 is a negative regulator of clock function in skeletal muscle in response to cancer." (PMID 40349340, 2025). "The FOXP1 ChIP-seq data were collected from the gastrocnemius-plantaris muscle complex, to provide sufficient starting material, whereas the RNA-seq experiments used the TA muscle, which is commonly used in cancer cachexia studies." (PMID 40349340, 2025). "Previous studies have demonstrated that FOXP1 plays contradictory roles in different cancers." (PMID 40672953, 2025). "Therefore, there is a need to perform a molecular pan-blood-cancer analysis of FOXP1 for an in-depth understanding of its role in different blood cancers." (PMID 40672953, 2025). "Recently, FOXP1 was found to play a crucial oncogenic role in several cancers." (PMID 40169859, 2025). "However a subset of REGs that lost rhythmicity in response to cancer in a FoxP1-dependent manner were direct FoxP1 target genes." (PMID 40349340, 2025). "Regarding FOXP1, it has a paradoxical role in tumorigenesis, depending on the type of cancer." (PMID 38684876, 2024). "Additionally, a unique deletion peak at 3p13 was observed in the responsive tumors, which contains the cancer related gene FOXP1." (PMID 38217005, 2024). "Emerging research showed the dual functions of FOXP1 protein in specific cancer types." (PMID 36952469, 2023). "Similarly, FOXP1 upregulation is sufficient to induce skeletal muscle wasting and weakness and is required for the normal wasting response in cancer." (PMID 36077789, 2022). "However, FOXP1 in Oncomine is up-regulated in cancer tissues and FOXP1 in TIME is up-regulated in normal tissues." (PMID 35614183, 2022). "In the context of cancer, FoxP1 knockdown blocked the cancer‐induced repression of myocyte enhancer factor 2 (MEF2)‐target genes critical to muscle differentiation and repair, improved muscle ultrastructure, and attenuated muscle fibre atrophy by 50% (P < 0.05)." (PMID 33527776, 2021). "In summary, we identify FoxP1 as a novel repressor of skeletal muscle gene expression that is increased in cancer cachexia, whose up‐regulation is sufficient to induce skeletal muscle wasting and weakness, and required for the normal wasting response to cancer." (PMID 33527776, 2021). "In fact, several truncated versions of FoxP1 were observed through western blots of skeletal muscle from mice and humans, with a smaller FoxP1 isoform between ~55 and 65 kDa showing increased abundance in response to cancer cachexia." (PMID 33527776, 2021). "Thus, future studies are needed to not only delineate the predominant FoxP1 isoforms expressed in skeletal muscle under baseline conditions and in response to cancer cachexia but to also determine their functional importance in muscle." (PMID 33527776, 2021). "Interestingly we found that FOXP1 and CAV1, genes that are commonly repressed by HMGA1 in cancer, were positively associated with HMGA1-lnc expression." (PMID 33505435, 2020). "Most importantly, FOXP1 or circFOXP1 overexpression was correlated with many cancers." (PMID 32996692, 2020). "Overall, NFAT1 closely interacts with FOXP1 or FOXP3 in cancer progression." (PMID 31815635, 2019). "It was approved by dozens of researches that FOXP1 may be a very valuable marker for cancer patients’ prognosis." (PMID 29934982, 2018). "Deciphering which of these partners, such as FOXP1, CtBP1, MAPK3, GATAD2B, might be involved in oncogenic process along with FOXP2 should improve our understanding of gene networks underlying cancer progression." (PMID 29725501, 2018). "We demonstrate that Foxp1-Shq1 deletion accelerates prostate tumorigenesis in mice in combination with Pten loss, consistent with the association of FOXP1-SHQ1 and PTEN loss observed in human cancers." (PMID 29057879, 2017).
cancer (continued). "The results showed that FOXP1 was significantly upregulated in the cancer tissues of 62 matched HCC/normal samples by qRT-PCR and 24 matched HCC/normal samples by Western blot analysis, and a similar result was confirmed in a 50-patient cohort from The Cancer Genome Atlas (TCGA)." (PMID 27618020, 2016). "EBV encodes 44 mature micro RNAs (miRNAs), but the roles of only a few EBV-encoded miRNA targets are known in cancer development, and here, our aim was to elucidate the effects of EBV-miR-BART11 on FOXP1 expression, and potential involvement in inflammation-induced carcinogenesis." (PMID 27167345, 2016). "This may have important implications for cancer immunotherapy and strengthens the case for the FOXP1 pathway as both a useful biomarker and a novel therapeutic target for restoring antigen presentation and immune surveillance in DLBCL." (PMID 26500140, 2016). "Collectively, these data demonstrate that EBV-miR-BART11 or FOXP1 may serve as potential diagnostic or prognostic markers in NPC or GC, and may represent important targets for EBV-related cancer immunotherapy." (PMID 27167345, 2016). "FOXP1 is widely expressed in normal human tissues and a diverse range of cancers." (PMID 27618020, 2016). "Functionally, FOXP1 protein expression has opposing effects in different types of cancer." (PMID 25663935, 2015). "Of the six proteins that were investigated via immunohistochemistry, four (cyclin D1, FOXP1, NRP1 and CD99) showed reduced expression in BRCA1 cancers in the initial cohort with reduced expression for FOXP1, cyclin D1 and NRP1 subsequently confirmed in the validation cohort." (PMID 26152113, 2015). "Compared with sporadic basal cancers, BRCA1 cancers showed reduced positivity for proteins predicted to be regulated by miRNAs: FOXP1 (6/20[30 %] vs. 37/49[76 %], p < 0.001), cyclin D1 (8/22[36 %] vs. 30/46[65 %], p = 0.025), NRP1 (2/20[10 %] vs. 23/46[50 %], p = 0.002)." (PMID 26152113, 2015). "Similarly, FOXP1 protein expression levels and localization vary depending on the tissue type and disease stages in cancer." (PMID 25663935, 2015). "BRCA1 basal cancers, when compared to sporadic basal cancers showed reduced positivity for FOXP1 (6/20 [30 %] vs. 37/49 [76 %], p < 0.001), cyclin D1 (8/22 [36 %] vs. 30/46 [65 %], p = 0.025), NRP1 (2/20 [10 %] vs. 23/46 [50 %], p = 0.002) and CD99 (17/20 [85 %] vs. 7/19 [37 %], p = 0.002)." (PMID 26152113, 2015). "FoxP1 is a transcriptional repressor that plays an important role in the development of the brain and lung in mammals and has been described to have diverse and opposing functions in different types of cancer." (PMID 25406647, 2014). "We selected novel epigenetic markers including NKIRAS1/RPL15, THRB RBPS3 (CTDSPL), IQSEC1, NBEAL2, ZIC4, LOC285205, CGGBP1, EPHB1 and FOXP1 that allowed detection of cancer in ovarian biopsies on all stages with sensitivity equal to (72 ± 11)% and specificity (94 ± 5)%." (PMID 23202957, 2012). "Deregulation of FOXO1 and FOXP1 had been shown in many cancer types." (PMID 21655267, 2011). "We further show that skeletal-muscle FoxP1 is a key mediator of these disruptions in response to cancer, which may be mediated, at least in part, through direct binding and dysregulation of core clock genes, clock-controlled genes, and genes involved in muscle catabolism." (PMID 40349340, 2025). "Thus, it is possible that FOXP1 bound to gene-regulatory regions in the context of cancer could directly interfere with the rhythmic induction of these genes by the clock transcriptional activators, BMAL/CLOCK." (PMID 40349340, 2025). "Furthermore, analysis of ICB therapy datasets suggested that cancer patients with low FOXP1 expression demonstrated higher ICB response rates and improved survival outcomes, including OS and progression-free survival in comparison to cancer patients with high FOXP1 expression." (PMID 40672953, 2025).